EGFR (epidermal growth factor receptor)
Diseases named in the same sentence as EGFR in open-access papers (continued):
Sharing a sentence is not in itself a finding about the gene and the disease.
tumor (continued). "addressed the heterogeneity of the mutations predicting the resistance to anti‐EGFR treatment (KRAS, NRAS, BRAF and/or PIK3CA) in the primary CRC tumours in the context of the proportion of neoplastic cells." (PMID 40302146, 2025). "Altogether, our study suggests that ER inhibition prevents tumor growth driven by EGFR/HER2 signaling, supporting the potential of combination therapies targeting both ER and HER2." (PMID 41224124, 2025). "Functional analysis of differential miRNAs in sEVs derived from CAL27 cells with varying EGFR levels further substantiated the role of EGFR-induced miRNA secretion in enhancing tumor angiogenesis." (PMID 39816681, 2025). "High expression of EGFR has been observed on the surface of cSCC Tumor Cells, while CD3 serves as a critical component of the TCR-CD3 complex on T cells, mediating the transmission of activation signals." (PMID 41333481, 2025). "In accordance with decoration levels, STAREGFR-T cells showed ability to exert specific cytotoxicity against EGFR+ tumor cells up to 72 hours after electroporation." (PMID 41341587, 2025). "It was unclear if they preferentially entered EGFR‐positive tumor cells over other cell types and then escaped from the lysosome for cytosolic delivery." (PMID 39263835, 2025). "By simultaneously targeting EGFR and MET receptor pathways in platinum-based chemotherapy-resistant cancer cases, amivantamab demonstrates both direct killing of tumor cells and enhanced cytolytic susceptibility." (PMID 40385479, 2025). "The study revealed that in tumor cells with an activated EGFR pathway, a multi-layered interplay exists." (PMID 41158851, 2025). "G31P has a dual action: it suppresses tumor-promoting chemokine signaling and mitigates pulmonary toxicity, making it a promising adjuvant for EGFR-TKI-based therapies." (PMID 41425704, 2025). "Immunohistochemistry (IHC) showed markedly decreased EGFR expression in the recurrent tumor, post-cetuximab, compared to strong plasma membrane EGFR labeling in the pre-treatment samples (Fig. 2Avs 2B, EGFR)." (PMID 40819143, 2025). "It was reported in multiple kinds of cancers, tumor‐associated macrophage (TAM) is associated with resistance to ICBs, and their interaction with EGFR signaling has significant implications for cancer progression and treatment response." (PMID 40859900, 2025). "By identifying genetic mutations (e.g., EGFR, KRAS) and predicting tumor behavior, AI enables more precise preoperative planning and risk stratification, guiding the extent of resection, lymph node dissection, or multimodal therapy selection." (PMID 40283559, 2025). "With tumor membrane protein EGFR taken as representative, the ELISA results showed that the Vpr peptides promoted the release of soluble membrane antigen proteins from tumor cells into the culture supernatant." (PMID 40733687, 2025). "Dysregulation of these pathways plays a pivotal role in tumor progression and therapeutic resistance, especially to EGFR inhibitors." (PMID 41375018, 2025). "This system achieved tumor-specific targeting via epidermal growth factor receptor (EGFR) recognition, demonstrating potent antitumor effects and reduced off-target toxicity in murine models." (PMID 40429976, 2025). "Two tumor characteristics are presently in use for this purpose: EGFR copy number (as established using fluorescence in situ hybridization) and K-ras gene mutation stage." (PMID 40722718, 2025). "The inhibition of EGFR signalling using monoclonal antibodies or small-molecule inhibitors has shown potential in mitigating SPINK 1-driven tumor growth." (PMID 40872585, 2025). "The study explored gene delivery using a GE11-conjugated polyethylenimine vector, which demonstrated successful uptake in EGFR-positive cells and tumor xenografts, highlighting its potential in targeted gene therapy." (PMID 40428099, 2025). "Functionalized MNPs conjugated with targeting ligands (e.g., EGFR antibodies) improve tumor-specific drug delivery, reducing systemic toxicity." (PMID 41012430, 2025).
tumor (continued). "In targeted therapy, nanoparticles carrying tyrosine kinase inhibitors (TKIs, such as icotinib or erlotinib) can specifically inhibit signaling pathways driven by EGFR or BRAF mutations, while simultaneously sensitizing tumor cells to ferroptosis inducers." (PMID 40416987, 2025). "Tumor antigens are in turn targeted via binding to either MICA via NKG2Drp or EGFR via EGFR scfv or epidermal growth factor (EGF) ligand." (PMID 40741595, 2025). "Its anti-tumor effect in vivo in the SCCmodel (A431 xenografts) is mediated by an interaction with both α7-nAChRand EGFR." (PMID 40264586, 2025). "Induction of an invasive phenotype selectively in p-EMT tumor cells depended on the activation of EGFR by AREG on fibroblasts." (PMID 40121428, 2025). "Nanobody-engineered CAR-T cells directed against membrane-proximal EGFR demonstrated that the hinge domain truncation, while compromising overall cellular functionality, significantly improved tumor-specific selectivity." (PMID 40474230, 2025). "EGFR-TKIs also upregulated MHC class I molecules on tumor cells, improving antigen presentation to T cells and enhancing immune recognition." (PMID 40733125, 2025). "Overexpression of EGFR, a tyrosine kinase of the ErbB receptor family, correlates with tumor grade, muscle invasion, and recurrence of BC, and therefore serves as a prognostic marker." (PMID 41471825, 2025). "Research has demonstrated that NT5DC2 is upregulated in TNBC, promoting tumor progression and neuropathic pain through interactions with the epidermal growth factor receptor (EGFR) to activate downstream signaling." (PMID 40109861, 2025). "Activation of the EGFR pathway significantly impacts cellular metabolism, fostering conditions that support rapid tumor growth and potentially contribute to treatment resistance." (PMID 40486879, 2025). "Established biomarkers, including IDH1, MGMT, and EGFR, provide crucial insights into the tumor's biology and are essential for guiding therapy decisions." (PMID 40223032, 2025). "This review outlines the current understanding of how EGFR, KRAS, and other key mutations influence immunotherapy responses and tumor immunology." (PMID 40524071, 2025). "Upregulation of mutant EGFR receptors or ligands can induce sustained EGFR activation, thereby fostering the proliferation and survival of tumor cells." (PMID 40732366, 2025). "Nimotuzumab, also known as h-R3, is an anti-EGFR humanized monoclonal antibody with anti-tumor effects." (PMID 40672372, 2025). "Multiple studies have reported that EGFR-mutant lung tumour tissues have a higher expression of PD-L1 more frequently than EGFR WT tumours." (PMID 40647497, 2025). "Considering that PD-L1 glycosylation is strongly influenced by EGFR signalling and other tyrosine kinases (TKs), TK inhibitors can synergize with PD-1 blockade to restore anti-tumor immunity." (PMID 41425548, 2025). "The results showed that there were was activated signaling of TNF, VEGFC and EGFR from TMGs-high epithelial niches to endothelial cells, indicating hyperactivated angiogenesis in tumor stromal tissues and a potential response to VEGF blockage." (PMID 40216815, 2025). "We confirmed that PCBP2 plays a crucial role in promoting EGFR-driven tumor angiogenesis both in vivo and in vitro, by controlling the secretion of these EVmotif-containing miRNAs." (PMID 39816681, 2025). "Specifically, its “tumor-targeting arm”—an anti-EGFR single-chain antibody fragment—selectively binds to EGFR on cSCC Tumor Cells, effectively anchoring T cells in close proximity to the Tumor Cells and minimizing off-target activation in non-tumor tissues." (PMID 41333481, 2025). "Based on our findings, we also tested the combination of entinostat and the EGFR inhibitor erlotinib in cell culture and in murine tumor xenografts." (PMID 39864337, 2025).
tumor (continued). "The mechanism by which EGFR influences tumor behavior and intercellular communication through the modulation of EV biogenesis and alteration of their cargo is not fully understood." (PMID 40210802, 2025). "Cetuximab not only inhibits tumor growth by blocking EGFR signaling, but also activates NK cells to induce ADCC." (PMID 40063100, 2025). "In vivo MRI experiments demonstrated that these peptide–Gd conjugates enabled EGFR-specific tumor imaging, with enhanced signal targeting EGFR-overexpressing tumor xenografts." (PMID 40906195, 2025). "This further elucidates the evolutionary distinction between the two NSD paths; when EGFR mutations are coupled with early WGD and substantial clonal copy number losses, this generally pushes tumours to the NSD-Loss trajectory." (PMID 41509216, 2025). "For instance, iron oxide NPs functionalized with HER x EGFR bsAbs using carbodiimide chemistry enabled MRI-based tumor imaging in mouse models." (PMID 41250091, 2025). "EGFR-mutated NSCLC is characterized by an immunosuppressive TME, leading to tumor evasion from immune surveillance." (PMID 40733125, 2025). "Collectively, EGFR orchestrates diverse immune cell behaviors, impacting tumor immunity, inflammation, and host defense." (PMID 40859900, 2025). "A previous study highlighted two protein degradation systems targeting lysosomes and proteasomes for EGFR, and EGFR stability is closely related to tumour occurrence and development." (PMID 39910656, 2025). "Several studies have shown that siRNA-mediated knockdown of tumor-associated genes such as TGM2, EGFR, and MUC1 in solid tumors can effectively reduce tumor proliferation and enhance apoptotic pathways." (PMID 41425727, 2025). "VEGF inhibitors, such as bevacizumab, disrupt tumor angiogenesis, while EGFR inhibitors like osimertinib or erlotinib target tumor cell proliferation." (PMID 39941694, 2025). "Both H-1975 and HCC827 cell lines are primarily resistant to EGFR-TKIs, thus making them typical tumor models for studying drug resistance." (PMID 40224214, 2025). "Next, we provide an overview of the EGFR imaging techniques developed using these targeting peptides and their recent applications in tumor diagnosis and treatment." (PMID 40906195, 2025). "First, during tumour initiation, driver mutations (such as KRAS^G12D or EGFR mutations) can only efficiently induce lesion formation in specific progenitor‐like or intermediate ‘damage/plasticity’ states." (PMID 40847555, 2025). "Several bispecific antibodies are in development for HNSCC, including those targeting EGFR and CD3 (to recruit T cells to EGFR-expressing tumor cells)." (PMID 40868227, 2025). "EGFR pathway activation also enhances tumour cell VEGF-A production, which interacts with VEGFR2 on endothelial cells to promote paracrine proliferation, migration, and differentiation." (PMID 41145684, 2025). "Consistent with the existing literature, we demonstrate the absence of expression of CD73 in normal alveolar tissue and expression in tumour cells, reflecting 66% CD73TC positivity, in line with prior data linking the expression of CD73 to EGFR mutations." (PMID 40149368, 2025). "From a histopathological perspective, the EGFR gene mediates vascular endothelial cell growth and promotes neovascularization, thereby facilitating rapid aggressive tumor progression." (PMID 41244899, 2025). "Mechanistically, ΔNp63α transcriptionally activates pro-survival genes (e.g., FGFR2, EGFR), and represses tumor suppressors (e.g., p73, p21)." (PMID 40223122, 2025). "For instance, the epidermal growth factor receptor (EGFR) is highly expressed on the surface of many epithelial-derived tumor cells, and certain stem cell-derived vesicles carry ligands that specifically bind to EGFR." (PMID 41425717, 2025). "Mechanistically, ANXA6 engages in interactions with EGFR and impedes the ubiquitin-proteasome pathway, thereby facilitating the accumulation of active EGFR and fostering tumor proliferation and dissemination." (PMID 40297849, 2025).
tumor (continued). "In NSCLC, SHP2 integrates upstream signals from oncogenic RTKs, such as EGFR, and KRAS mutations, sustaining tumor growth and resistance to therapeutic interventions." (PMID 40699708, 2025). "Beyond its role in tumor progression, YAP/TEAD-mediated signaling has recently been associated with resistance to targeted therapies in other tumor entities, such as KRAS- or EGFR-mutated cancers." (PMID 40649713, 2025). "Since TGFβ also modulates the tumor microenvironment, we next tested the microenvironmental effects of EGFR-low versus EGFR-high cells." (PMID 39747003, 2025). "Mechanistically, UBASH3B promotes tumor progression by stabilizing the epidermal growth factor receptor (EGFR) levels, thereby enhancing downstream signaling pathways that promote cancer cell proliferation, survival, and therapeutic resistance." (PMID 40885971, 2025). "Considering the enhanced proliferation and transduction efficiency of the TNK-polarized cells, this culture was further employed to assess its cytotoxic effects on EGFR-expressing tumor cells." (PMID 40002679, 2025). "Second, activated EGFR signaling in macrophages drives the secretion of cytokines to affect tumor cells." (PMID 40859900, 2025). "Found in 30–40% of cases, these mutations promote persistent activation of oncogenic pathways such as MAPK/ERK and PI3K/AKT, contributing to tumor growth, poor prognosis, and reduced responsiveness to anti-EGFR therapies." (PMID 39941797, 2025). "Gene amplification and increased expression of c-Myc in PDO 1 and EGFR in PDO 5 can explain the increased lactate labeling from hyperpolarized [1-13C]pyruvate observed in these tumor models." (PMID 39639170, 2025). "Applying the novel consensus mimics to xenograft models of PM and NSCLC in vivo using EGFR-targeted nanocells loaded with mimic led to tumour growth inhibition." (PMID 40121357, 2025). "Aside from AS, lipid metabolism targeting creates new opportunities as cancer cells rely on cholesterol-rich areas (rafts) to support survival signals (such as the EGFR/PI3K pathways), cholesterol imbalance causes AS, and is associated with tumor growth." (PMID 41304832, 2025). "Elevated expression of EGFR correlates with tumor cell proliferation, angiogenesis, invasion, metastasis, and the inhibition of apoptosis." (PMID 40732366, 2025). "Studies considering various tumor types have reinforced the importance of cell cycle suppression by inducing cell entrapment in G0/G1 through the inhibition of EGFR/MAPK and PI3K/mTOR." (PMID 40650170, 2025). "In glioblastoma, long eccDNAs carrying EGFR amplicons form a super-enhancer structure, driving the sustained activation of oncogenes and thus influencing the tumor progression." (PMID 40641599, 2025). "For the first time, we uncovered how EGFR overexpression governs miRNA contents within EVs derived from tumor cells, specifically focusing on their functional roles and the sorting mechanisms involved." (PMID 39816681, 2025). "In our study, all four cases with EGFR amplification exhibited high-grade histologic features, including micropapillary, complex glandular structures, solid nests, and tumor necrosis." (PMID 40310364, 2025). "Nevertheless, many receptor tyrosine kinases, particularly the epidermal growth factor receptor (EGFR), are often overexpressed in tumour cells." (PMID 40830825, 2025). "By preventing autophagy-mediated EGFR degradation, increased glycolysis can sustain high EGFR expression and further support tumor cell survival and proliferation." (PMID 40303296, 2025). "Phytochemicals inhibit these oncogenic cascades through direct inhibition of EGFR signaling, thus impairing tumor development and inducing programmed cell death in tumor cells." (PMID 40115248, 2025). "This case is the first to report that ACTL therapy has achieved “clinical cure” in a patient with acquired EGFR-TKI resistance, indirectly suggesting the underlying mechanism of this therapy in reshaping the tumor immune microenvironment (TME)." (PMID 40959071, 2025).
tumor (continued). "Innovative approaches such as dual-targeting (e.g., EGFR and EGFRvIII) have shown superior anti-tumor effects by preventing antigen escape, a common issue in CAR-T cell therapies." (PMID 40260240, 2025). "A high EGFR copy number using fluorescence in situ hybridization has a link with an increasing rate of tumor response and prolongation of disease-free and overall survival." (PMID 40722718, 2025). "For instance, inhibition of PRMT1 or treatment with PRMT1 inhibitors (e.g., AMI-1, C7280948) increases tumor sensitivity to the EGFR monoclonal antibody cetuximab and to PARP inhibitors such as olaparib." (PMID 41204384, 2025). "Early tumor evolution is marked by CDKN2A/B loss and EGFR, platelet-derived growth factor receptor A (PDGFRA), and CDK4 gains." (PMID 40565099, 2025). "On the one hand, tumor cell C1_EGFR+ and C2_STAT1+ directly act on CD8T_GNLY+ through the MDK–(ITGA4+ITGB1) axis and the MIF–(CD74+CXCR4) axis to promote tumor proliferation." (PMID 40948762, 2025). "By targeting tumor-associated antigens, such as CD33 or EGFR, while simultaneously inhibiting checkpoint pathways like PD-1/PD-L1 or CTLA-4, CiTEs overcome immune suppression within the tumor microenvironment and restore T-cell activation." (PMID 39982231, 2025). "EGFR‐targeted LNP resulted in higher expression of luciferase in the tumor bed, along with a prominent immunofluorescent‐staining signal when stained for luciferase antibody, compared to naked LNPs or isotype‐LNPs." (PMID 39736115, 2025). "First, its antigen-binding fragment (Fab) specifically binds to the epidermal growth factor receptor (EGFR), inhibiting its activity and blocking the subsequent intracellular signaling pathways within tumor cells." (PMID 40869384, 2025). "The baseline EGFR expression levels of the five tumor cell lines MDA-MB-231, A549, SGC-7901, SW480, and U138MG were confirmed by Western blot analysis." (PMID 41325799, 2025). "The study developed a validated non-invasive model (RS-BTIplusVPE) based on integrating BTI-based radiomics features and VPE, which showed improved prediction of EGFR-TKI response in NSCLC patients with BM compared to tumor-focused models." (PMID 40438144, 2025). "OmniCAR employs a truncated SpyCatcher ectodomain paired with SpyTag-equipped antibodies or designed ankyrin repeat proteins (DARPins), demonstrating in vivo efficacy targeting CD20, Her2, EpCAM, or EGFR tumours." (PMID 41465327, 2025). "Epidermal growth factor (EGF) signaling is the first step in activating glycolysis, and inhibition of EGF receptor (EGFR) inhibits cancer cell proliferation and tumor growth." (PMID 40309242, 2025). "OAd5NULL-A20-BICA aims to overcome this limitation by targeting two separate tumor antigens αvβ6 and EGFR simultaneously." (PMID 40741595, 2025). "Genetic alterations that lead to aberrant EGFR activation result in sustained signaling, thereby driving tumor growth, proliferation, and angiogenesis." (PMID 41590502, 2025). "At the tumor’s leading edge, EGFR promotes lipid metabolism and fatty acid synthesis to support membrane biogenesis and cell proliferation." (PMID 39859381, 2025). "For example, the feedback activation of EGFR has been demonstrated to attenuate lenvatinib efficacy, and the combinatorial application of EGFR inhibitors with lenvatinib surmounts tumor drug resistance." (PMID 40336047, 2025). "Models based on radiomic analysis, using machine learning, can identify imaging features that correlate with the molecular status of a tumor, such as IDH1 mutation, MGMT promoter methylation, or EGFR amplification." (PMID 41465586, 2025). "We have also identified specific enzyme targets of ambrosin, such as EGFR and RhoC, which are of interest due to their role in the metastatic progression of several tumor types." (PMID 40754248, 2025).